METTL3 (methyltransferase 3, N6-adenosine-methyltransferase complex catalytic subunit)
Diseases named in the same sentence as METTL3 in open-access papers (continued):
Sharing a sentence is not in itself a finding about the gene and the disease.
tumor (continued). "Studies have shown that METTL3-deficient mice exhibit tumor infiltration by M1/M2-like tumor-associated macrophages and regulatory T cells." (PMID 39759516, 2024). "Enrichment analysis revealed that METTL3 is involved in multiple pathways associated with tumour development." (PMID 38429907, 2024). "METTL3, a key protein closely associated with tumour progression and recently discovered, requires further exploration regarding its functional role in the invasion and metastasis of NSCLC." (PMID 38238831, 2024). "Analogously, Mettl3 is closely associated with multiple adverse biological behaviors of gynecologic malignancies, including tumor proliferation, apoptosis, metastasis, angiogenesis, and immune microenvironment." (PMID 37007040, 2023). "Deletion of METTL3 in papillary thyroid carcinoma promotes recruitment of tumor-associated neutrophils by eliciting secretion of IL-8, therefore supporting tumor progression." (PMID 37928272, 2023). "In fact, the loss of METTL3 or METTL14 enhances the interaction between the tumor and the immune system through the IFN-γ-STAT1-IRF1." (PMID 37427112, 2023). "Mettl3, which is highly expressed in OC, is associated with the tumor grade, size of the tumor, lymph node metastasis, distant metastasis, FIGO stage, and overall survival rate." (PMID 37007040, 2023). "A study found that METTL3 expression was upregulated in tumor-infiltrating myeloid cells (TIMs) and associated with poor prognosis." (PMID 37771377, 2023). "A deficiency of METTL3 also influences macrophage reprogramming and enhances tumor progression in other tumor mouse models." (PMID 39872957, 2023). "The reduced volume and weight of tumor nodules caused by USP13 silence was found to be counteracted by ectopic overexpression of METTL3 in 143B cells." (PMID 37151889, 2023). "In BC, the expression of METTL3 is positively associated with the tumor infiltration of CD8 + T cells, helper T cells and activated NK cells, and is negatively associated with the expression of PD-L1 and PD-L2." (PMID 36810108, 2023). "Consistent with the findings, a study found that loss of METTL3 dramatically repressed cancer cell proliferation, invasion, and xenograft tumor formation via AFF4, NF-κB, and MYC signaling networks." (PMID 39872957, 2023). "METTL3 is also upregulated in tumor-associated macrophages (TAMs) in patients with CRC with oxaliplatin resistance and downregulates TRAF5, inhibiting necroptosis, similar to its role in GC." (PMID 37965577, 2023). "To illustrate, METTL3, which is an RNA methylation enzyme, is inextricably linked to the process of RNA methylation in tumor cells." (PMID 38053093, 2023). "In summary, all current studies suggest that high expression of Mettl3 in OC causes adverse biological behaviors and promotes tumor development." (PMID 37007040, 2023). "Consistently, METTL3 knockdownwas associated with increased apoptosis, decreased cell proliferation,and tumor growth impairment both in vitro and in vivo." (PMID 36692498, 2023). "Silencing METTL3 caused papillary thyroid cancer cells to secrete more pro-inflammatory factors, particularly IL-8, which can recruit infiltration of tumor-associated neutrophils." (PMID 37671161, 2023). "In this study, elevated METTL3 expression was associated with promoted proliferation of HB cells, in accord with findings that pronounced METTL3 mRNA levels in HB tumours correlated with decreased survival rate among patients." (PMID 35604883, 2022). "Further analysis of PC data from the database showed that METTL3 expression was associated with a variety of tumor-infiltrating immune cells and was involved in m6A modification and metabolism in PC tissues." (PMID 36058919, 2022). "In normal tissues, paracancerous tissues and tumor tissues, the expression level of m6A exhibits a gradually increasing trend, and this change is mainly caused by increased expression of METTL3." (PMID 35155557, 2022).
tumor (continued). "Further analysis from the database showed that METTL3 expression was associated with a variety of tumor-infiltrating immune cells and was involved in m6A modification and metabolism in PC tissues." (PMID 36058919, 2022). "Mice conditionally deficient for METTL3 in NK cells exhibited aggressive tumor progression, suppressed effector functions of NK cells and shortened survival time." (PMID 36085064, 2022). "Consistently, IHC results also showed that CDC25B staining was also obviously decreased in tumor xenograft with deficiency of METTL3." (PMID 35287752, 2022). "METTL3 was frequently upregulated in OC and that a high level of METTL3 was significantly associated with higher tumor grade." (PMID 35813486, 2022). "Many studies have shown that METTL3 promotes tumor growth and aggressiveness by regulating the mRNA decay and stability or mRNA translation of numerous tumor-associated genes, such as SOCS2, BATF2, EGFR, TAZ, MAPKAPK2, and DNMT3A." (PMID 35456475, 2022). "Multiple m6A methylation regulators have been shown to be associated with prognosis of different tumor types, including METTL3, WTAP, IGF2BP, FTO, and YTHDF." (PMID 35794625, 2022). "High level of METTL3 was associated with the incidence of lymphatic metastasis, large tumor size, advanced tumor staging, and low overall survival of HCC." (PMID 35571490, 2022). "METTL3 is downregulated in tumor-infiltrating NK cells within the TME caused by TGF-β, which activates m6A-mediated fragile effector function and limits the terminal differentiation of peripheral NK cells." (PMID 35864970, 2022). "METTL3 is a key regulator that promotes m6A modification, and the abnormal regulation of METTL3 is also inextricably linked to tumor development." (PMID 35707365, 2022). "Other studies also demonstrated that the expression levels of METTL3 was intimately associated with tumour size and histological grade." (PMID 36118874, 2022). "Loss of METTL3 promotes tumor growth, increased susceptibility to bacterial infection in vivo and reduced TNF-α secretion by macrophages in vitro." (PMID 36085064, 2022). "We next investigated if ASP/NAM co-treatment can induce METTL3 acetylation and subsequent m6A-associated alterations in tumor xenografts." (PMID 36289222, 2022). "The homeostasis of NK cells was changed with loss of METTL3 in NK cells, and infiltration and function of NK cells were inhibited in tumor microenvironment, which resulted in increasing rate of tumor growth and reduced survival time in mice." (PMID 36545327, 2022). "M2-polarized tumor-associated macrophages can elevate the level of m6A modification mediated by METTL3 and induce oxaliplatin (OX) resistance." (PMID 34976168, 2022). "Recent studies found that METTL14, METTL3, and their target genes, Spred2 and Irakm, in macrophages are associated with tumor progression." (PMID 35296338, 2022). "Consistent with this, elevated METTL3 expression has been associated with more advanced tumour stage and a poorer prognosis, whereas reduced METTL3 expression has been linked with advanced metastatic PCa." (PMID 36733939, 2022). "A number of recent studies have revealed that METTL3 is upregulated in PCa, and that this increased expression promotes migration and invasion of PCa cells, tumour growth, and is associated with higher tumour stage and poorer prognosis." (PMID 36733939, 2022). "In line with our study, a loss of METTL3 or METTL14 in CRC was reported to promote IFN-γ-Stat1-Irf1-signaling in an m6A-dependent manner to regulate anti-tumor immune responses upon anti-PD-1 therapy." (PMID 36009465, 2022).
tumor (continued). "METTL3 levels were significantly related to immune cell infiltration, tumor mutation burden, microsatellite instability, mismatch repair genes, and immune checkpoint gene levels." (PMID 36614956, 2022). "Ablating METTL3 in macrophages also increased susceptibility to bacterial infection and tumor growth." (PMID 35296338, 2022). "We found that Mettl3-deficient TAMs expressing relatively high levels of CCL22 were responsible for Treg recruitment within the complex tumour microenvironment." (PMID 33654093, 2021). "Treg depletion abrogated the enhanced tumour growth and metastasis observed in Mettl3-deficient mice." (PMID 33654093, 2021). "Our findings indicate that FBXW7 expression is positively associated with METTL3 at the protein level and exerted a crucial tumor suppressor function in carcinogenesis." (PMID 33676554, 2021). "It is well known that higher METTL3 is associated with advanced stage and distant metastasis, indicating the tumor-promoting role of METTL3 in NPC." (PMID 33879256, 2021). "In summary, these data suggested that Mettl3-deficient macrophages reshaped the tumour microenvironment by regulating cytokine responses." (PMID 33654093, 2021). "Collectively, these results indicate that FBXW7 overexpression rescues the impaired anti-tumor phenotype caused by METTL3 knockdown." (PMID 33676554, 2021). "Mice conditionally deficient for METTL3 in NK cells have aggravated tumor progression, accompanied by a reduced number and impaired effector functions of NK cells." (PMID 34535671, 2021). "From in vivo bioluminescence imaging, we observed that METTL3 KD caused a significant reduction in tumor size and promoted TMZ sensitivity with respect to the control cells." (PMID 34586728, 2021). "To determine the mechanism underlying METTL3-promoted tumour cell proliferation, we examined the role of METTL3 in epitranscriptomal regulation in ESCC cells." (PMID 34155197, 2021). "This implied that Mettl3-deficient myeloid cells contributed to B16 tumour resistance to anti-PD-1 therapy." (PMID 33654093, 2021). "In contrast to wild-type mice, Mettl3-deficient mice show increased M1/M2-like tumour-associated macrophage and regulatory T cell infiltration into tumours." (PMID 33654093, 2021). "Increasing evidence demonstrated that m6A modification is associated with TME of cancer, and the polarization of tumor-associated macrophages-M2 enabled the oxaliplatin resistance via the elevation of METTL3-mediated m6A modification." (PMID 34332578, 2021). "Our results showed that the expression of ARG1 was markedly upregulated in Mettl3-deficient myeloid cells, enhancing tumour growth and metastasis." (PMID 33654093, 2021). "Recent studies have revealed m6A methylation components can act as tumor-associated factors, including “writers” (METTL3/14, WTAP and KIAA1429), “erasers” (FTO and ALKBH5), and “readers” (YTHDF1/2/3, HNRNPA2B1, BCDIN3D)." (PMID 33791305, 2021). "It has been reported that cytotoxic tumor-infiltrating CD8+ T cell is increased in METTL3 or METTL14 deficient tumor." (PMID 34616403, 2021). "Considering the reduced number of NK cells and suppressed effector functions of tumor-infiltrating NK cells in cKO mice, we wondered if METTL3-deficient NK cells were defective in their response to IL-15." (PMID 34535671, 2021). "High METTL3 expression in the tumour and in tumour-infiltrating immune cells was linked to tumour stage (P = 0.040 and 0.020, respectively)." (PMID 33059689, 2020). "Here we summarize our current understanding both on the oncogenic and tumor-suppressive functions of METTL3, as well as the underlying molecular mechanisms." (PMID 32854717, 2020). "We observed increased levels of METTL3 and CD33+ MDSCs in tumour tissues and positive associations between the levels of METTL3 and CD33+ MDSCs." (PMID 33059689, 2020). "We next assessed the association between the intensity of METTL3, glycolysis components, and disease-free survival after tumor resection in this patients’ cohort." (PMID 32245489, 2020).
tumor (continued). "Our data identified a positive association between METTL3 expression in tumour cells and in tumour-infiltrating immune cells and intratumoural CD33+ MDSC density." (PMID 33059689, 2020). "We also found that overexpression of METTL3 is associated with tumor size and histological differentiation in ESCA patients." (PMID 32626532, 2020). "The authors also showed that upregulated METTL3 in ovarian carcinoma was significantly associated with tumor grade and overall survival rate." (PMID 32854717, 2020). "METTL3 expression was significantly associated with tumor size (p = 0.011) and distant metastasis (p = 0.040) and TNM stage (p = 0.035)." (PMID 32175271, 2020). "In NPC, METTL3 is negatively associated with tumor repressor ZNF750, which is part of a ZNF750-FGF14 signaling axis that inhibits NPC growth." (PMID 32513173, 2020). "A significant positive association between METTL3 expression was observed with tumor stage and metastasis." (PMID 32284755, 2020). "High METTL3 expression was associated with tumor differentiation (P = 0.002), tumor size (P = 0.018), microvascular invasion (P = 0.023), TNM stage (P = 0.001), and unfavorable overall survival." (PMID 31915027, 2020). "METTL3 is implicated in many aspects of tumor progression, including tumorigenesis, proliferation, invasion, migration, cell cycle, differentiation, and viability." (PMID 31921660, 2019). "In univariate analysis, the survival of RCC patients was significantly associated with age (P=0.005), tumor size (P=0.015), histological grade (P=0.000), tumor stage (P=0.000) and METTL3 expression (P=0.049)." (PMID 29221190, 2017). "Transcriptomic profiling identifies ADAM23, a cell-adhesion-related tumor suppressor, as a METTL3-dependent, m6A-associated transcript, with altered mRNA expression observed across multiple experimental systems and several high-confidence predicted m6A sites within its transcript." (PMID 41677656, 2026). "Notably, BMP10 overexpression or rBMP10 supplementation effectively mitigated the tumor-promoting effects of METTL3-deficient HSCs." (PMID 42030359, 2026). "Many studies have shown that METTL3 is associated with the processes involved in the progression of gastrointestinal cancer, including regulation of mRNA and noncoding RNA, maturation, translation, and tumor progression." (PMID 41517663, 2026). "METTL16 serves as a favorable prognostic biomarker because of its association with improved survival outcomes, whereas METTL3 may influence tumor progression through RNA metabolic reprogramming." (PMID 40986143, 2025). "Loss of METTL3 impairs translation of tumor-suppressive genes, enhancing NF-κB and STAT3." (PMID 40868849, 2025). "Notably, it has been reported that the expression of these chemokines, specifically CXCL9 and CXCL10, is upregulated in the tumor microenvironment of METTL3-deficient tumors." (PMID 39497707, 2025). "Similarly, AF127577.4-ORF, encoded by AF127577.4 lncRNA, exerts its tumor-suppressive function by decreasing global m6A levels by reducing the stability of the m6A methyltransferase METTL3 through disruption of the ERK2/METTL3 interaction." (PMID 40361481, 2025). "Conversely, a deficiency of METTL3 in myeloid cells reduces tumor growth in mouse models." (PMID 39802639, 2025). "Inhibiting FGF2 reversed the tumor-promoting effects caused by METTL3 downregulation in LUAD cells." (PMID 39497721, 2024). "Additionally, a subcutaneous tumor model in nude mice demonstrated that loss of METTL3 significantly inhibited the tumorigenic ability of EC109 cells, while loss of METTL14 did not significantly affect tumor growth." (PMID 38965238, 2024). "In addition to TLR4, c-Rel and RelA have been identified as crucial downstream targets of METTL3 in tumor-associated neutrophils (TANs)." (PMID 38322265, 2024).
tumor (continued). "Additionally, we found that DLAT expression was significantly higher in the high METTL3 expression group than in the low expression group, highlighting the potential association between these two genes in cuproptosis‐related tumour development." (PMID 38429907, 2024). "In contrast, METTL3 is usually associated with tumor drug resistance." (PMID 38166703, 2024). "Furthermore, mice with a specific knockdown of Mettl3 in macrophages (Mettl3fl/fl; Lyzm-Cre mice model) are more susceptible to bacterial infection and exhibit faster tumor growth." (PMID 39416774, 2024). "In myeloid cells, the ablation of METTL3 could promote tumor metastasis, which was due to the deficiency of METTL3 increased the M1 macrophages and regulatory T cells infiltration." (PMID 38637813, 2024). "Similarly, Mettl3 was found to be highly expressed in cancerous tissues, and overexpression of Mettl3 was an independent risk factor for higher tumor grade as well as for lower overall survival." (PMID 37007040, 2023). "Previous research indicated that the loss of the m6A methylation eraser METTL3 could lead to tumor metastasis and EMT46." (PMID 37907576, 2023). "Back to METTL3, its oncogenic activity has also been linked to tumor formation in CRC where m6A methylation of lncRP11 increases its nuclear accumulation, drives Siah1 and Fbxo45 mRNA degradation, and prevents ZEB1 mRNA decay, thus, regulating EMT and liver metastasis." (PMID 37369946, 2023). "In macrophages, deletion of Mettl3 limited the expression of inflammatory cytokines in response to LPS and impaired effector responses, leading to increased susceptibility to bacterial infection and uncontrolled tumor growth." (PMID 37386028, 2023). "What’s more, with respect to RNA methylation, numerous vitro models and mice models have confirmed that by reducing the infiltration of M1 macrophages and Treg cells in TME, Mettl3-deficient mice displayed faster tumor growth and attenuated therapeutic efficacy of PD-1 checkpoint blockade." (PMID 37273004, 2023). "In addition, M2-polarized tumor-associated macrophages can induce OX resistance by improving METTL3-mediated m6A modification." (PMID 36791151, 2023). "Importantly, METTL3 has been implicated in human malignancy, acting as either an oncogene or a tumor suppressor." (PMID 38012755, 2023). "Inhibited expression of Mettl3 was detected along with the loss-of-function mutation of Mettl14 and reduced m6A levels in EC tissues, and it was correlated with the proliferative effects of tumor cells." (PMID 37007040, 2023). "In contrast with the findings discussed thus far, two studies have provided evidence suggesting that METTL3, and the associated increase in m6a levels, may have a tumour-suppressive role in GBM." (PMID 37444417, 2023). "In recent years, many studies have reported that METTL3 could lead to changes in the expression of target genes through the regulation of mRNA translation process, which in turn caused tumor progression." (PMID 36830614, 2023). "Strikingly, ablation of METTL3 in myeloid cells promoted tumor growth and metastasis, associated with decreased YTHDF1-mediated translation of SPRED2 and increased activation of NF-kB and STAT3 through the ERK pathway, leading to increased tumor growth and metastasis." (PMID 37369946, 2023). "METTL3 deficiency in TIMs restricted tumor growth and the immunosuppression of TIMs." (PMID 37152066, 2023). "METTL3, an RNA methyltransferase, is associated with clinical prognosis in various carcinomas; however, whether it acts as an oncogene or a tumor suppressor depends on what gene is targeted in the carcinoma." (PMID 35773310, 2022). "Furthermore, PD-1 checkpoint blockade was partially decreased in Mettl3-deficient mice, indicating the important role of Mettl3 in tumor immunotherapy." (PMID 36225914, 2022).